SLC12A2 (solute carrier family 12 member 2)
Diseases named in the same sentence as SLC12A2 in open-access papers (continued):
Sharing a sentence is not in itself a finding about the gene and the disease.
breast carcinoma (5 papers, 2014 to 2026). "Antihypertensive drugs increase the overall risk of breast cancer and ER + breast cancer within the SLC12A2 gene." (PMID 42260808, 2026). "Mediation analyses suggested that the pathway related to intestinal ischemia mediated 73.711% of the total effect on over breast cancer risk in the SLC12A2 gene loci." (PMID 42260808, 2026). "Colocalization analysis showed that SLC12A2-targeted drugs share a common variant site with breast cancer." (PMID 42260808, 2026). "Another dataset indicated SLC12A2 expression in blood platelet from patients with breast carcinoma was lower than that from healthy controls (log fold change = − 3.3, p-value = 7.7 × 10–24)." (PMID 38396187, 2024). "Combined with the results of SMR analysis and drug-targeting MR analysis, loop diuretics aggravated overall breast cancer (OR_SMR = 0.842, 95% CI_SMR: 0.778-0.911, P_SMR_FDR = 0.008) and ER + breast cancer (OR_SMR = 0.854, 95% CI_SMR: 0.778-0.937, P_SMR_FDR = 0.008) within SLC12A2 gene loci." (PMID 42260808, 2026).
Kilquist syndrome (5 papers, 2020 to 2022). An autosomal recessive multisystem disorder characterized by neurologic, gastrointestinal, and secretory dysfunction. "Mutations in SLC12A2, encoding NKCC1, have been associated with a rare genetic syndrome known as Kilquist syndrome featuring sensorineural deafness, intestinal and respiratory dysfunction, neuropsychological delay, and severe xerostomia (autosomal recessive; loss of function)." (PMID 36295670, 2022). "SLC12A2 (MIM No. 600840) has recently been reported to be involved in ADNSHI DFNA78, AD Delpire–McNeill syndrome (MIM: 619083), and AR Kilquist syndrome (MIM: 619080)." (PMID 34226616, 2021).
male infertility (4 papers, 2016 to 2022). The inability of the male to effect fertilization of an ovum after a specified period of unprotected intercourse. "In addition, Slc12a2-deficient M. musculus exhibit hearing loss, vestibular defects, and additional symptoms, including small body size, hyper-excitability, and male infertility." (PMID 32294086, 2020).
adenoma (3 papers, 2019 to 2025). A neoplasm arising from the epithelium. "In adenoma-normal, we found upregulation of SLC12A2, which encodes the basolateral ion transporter NKCC1." (PMID 31211760, 2019). "In isolated adenoma samples, among 5 paired miRNAs/mRNAs, 3 pairs (hsa-miR-34a-5p/SLC12A2, hsa-miR-15a-5p/SLC12A2, and hsa-miR-195-5p/SLC12A2) were retained in single regression analysis." (PMID 35875068, 2022). "Similar to our results, adenoma-specific stem cells were shown to originate from TIC-like populations expressing ETS2, SLC12A2, and LEFTY1." (PMID 41282138, 2025). "According to these criteria, the following five pairs of miRNAs/mRNAs were retained among 57 pairs in the adenoma samples: hsa-miRNA-34a-5p/SLC12A2 (solute carrier family 12 member 2), hsa-miRNA-15b-5p/SLC12A2, hsa-miRNA-195-5p/SLC12A2, hsa-miRNA-15a-5p/SLC12A2, and hsa-miRNA-3907/EEF1A1." (PMID 35875068, 2022). "Specific paired miRNA/mRNA networks, including hsa-miR-34a-5p/SLC12A2, hsa-miR-15b-5p/SLC12A2, hsa-miR-195-5p/SLC12A2, hsa-miRNA-502-3p/OLFM4, hsa-miRNA-6807-5p/ZG16, and hsa-miRNA 3064-5p/SH3BGRL3, were identified in samples of adenoma, IMC, and CRC with the MSS phenotype." (PMID 35875068, 2022).
cyst (3 papers, 2022 to 2025). A sac-like closed membranous structure that may be empty or contain fluid or amorphous material. "Furthermore, the CFTR (cystic fibrosis transmembrane conductance regulator), the Ca2+-activated chloride channels TMEM16A (Anoctamin 1), but also the SLC member Slc12a2 have been identified as crucial aggravating co-factors for cyst enlargement in polycystic kidney disease." (PMID 35252349, 2022).
metabolic syndrome (3 papers, 2022 to 2024). A cluster of metabolic risk factors for CARDIOVASCULAR DISEASES and TYPE 2 DIABETES MELLITUS. "Among the genes that exhibit interaction with CACNA1E, the SLC12A2 gene, which encodes the solute carrier family 12 (sodium/potassium/chloride transporter) member 2, has been recently associated to metabolic syndrome in mice." (PMID 39273144, 2024).
sensorineural hearing loss (3 papers, 2020 to 2021). "In this study, we identified four candidate variants of SLC12A2 in four families with sensorineural hearing loss." (PMID 32294086, 2020).
colorectal cancer (2 papers, 2024 to 2025). A primary or metastatic malignant neoplasm that affects the colon or rectum. "For instance, SLC12A2 was found to enhance invasion, proliferation, and migration of colorectal cancer cells while inhibiting apoptosis." (PMID 40040720, 2025). "This analysis aimed to compare the expression levels of SLC12A2 across these different cell lines to better understand its potential role in colorectal cancer." (PMID 40040720, 2025). "We first analyzed SLC12A2 expression in the normal colonic epithelial cell line HCoEpiC, as well as in the following four colorectal cancer cell lines: SW480, SW620, LOVO, and HCT15." (PMID 40040720, 2025). "We also found that the expression levels of SLC12A2 were significantly higher in colorectal cancer cell lines than in normal cell counterparts, suggesting its potential role in cancer development." (PMID 40040720, 2025). "Based on the results, it can be concluded that SLC12A2 plays an oncogenic role in colorectal cancer cells, promoting their proliferation, invasion, and migration." (PMID 40040720, 2025). "A marked upregulation of SLC12A2 in colorectal cancer cells was observed (p < 0.05)." (PMID 40040720, 2025). "Furthermore, SLC12A2 knockdown significantly reduced the viability of colorectal cancer cells, increased apoptosis, and diminished both migratory and invasive capabilities." (PMID 40040720, 2025). "The findings of the CCK-8 assay demonstrated that silencing SLC12A2 led to a marked decrease in the viability of SW620 and LOVO colorectal cancer cells." (PMID 40040720, 2025). "Transwell assay results showed that SLC12A2 knockdown significantly impaired the invasive capacities and the migratory of SW620 and LOVO cells, suggesting that SLC12A2 is crucial for the metastatic potential of colorectal cancer cells (p < 0.01)." (PMID 40040720, 2025).
Insulin resistance (2 papers, 2022 to 2023). Increased resistance towards insulin, that is, diminished effectiveness of insulin in reducing blood glucose levels. "Male mice lacking the Na+-K+-2Cl– cotransporter Slc12a2 (Nkcc1) specifically in insulin-secreting β-cells (Slc12a2βKO) have reduced β-cell mass and mild β-cell secretory dysfunction associated with overweight, glucose intolerance, insulin resistance, and metabolic abnormalities." (PMID 37819196, 2023). "We have recently demonstrated that male mice lacking Slc12a2 in insulin-secreting β-cells develop overweight, hyperlipidemia, glucose intolerance, insulin resistance, and steatohepatitis spontaneously without overeating." (PMID 37819196, 2023).
Tinnitus (2 papers, 2016 to 2017). Tinnitus is an auditory perception that can be described as the experience of sound, in the ear or in the head, in the absence of external acoustic stimulation. "KCNE1 and SLC12A2 were associated with tinnitus based on significance in only one genetic marker per gene (rs915539 in KCNE1, p = 0.018; rs10089 in SLC12A2, p = 0.026)." (PMID 28533738, 2017).
autosomal dominant nonsyndromic hearing loss (1 paper, 2020). Autosomal dominant form of nonsyndromic deafness. "Therefore, we propose that mutations in SLC12A2 are associated with autosomal-dominant nonsyndromic hearing loss." (PMID 32294086, 2020).
bowel obstruction (1 paper, 2026). "NKCC1, encoded by SLC12A2, is a key basolateral cotransporter, and patients with SLC12A2 mutations present with severe gastrointestinal dysfunction, including bowel obstruction and constipation." (PMID 41503704, 2026).
colorectal adenoma (1 paper, 2022). An adenoma that arises from the colon or rectum. "In gastrointestinal tumors, including colorectal adenomas, the functions of SLC12A2 have not been fully elucidated." (PMID 35875068, 2022).
Inguinal hernia (1 paper, 2020). Protrusion of the contents of the abdominal cavity through the inguinal canal. "We found variants at nine loci to associate with POP; five of which associate at genome-wide significance with POP, three that were previously associated with height (P < 1.4 × 10−5) at TXNDC5 (6p24.3), SLC12A2 (5q23.3) and LOXL1 (15q24.1) and one at WT1 that associates with inguinal hernia (11p13)." (PMID 32184442, 2020).
malignant mesothelioma (1 paper, 2019). A malignant neoplasm of the pleura or peritoneum, arising from mesothelial cells. "SLC12A2 plays a role in Na+, K+, and 2Cl-cotransporter in membrane blebbing via interactions with actin and the p38 mitogen-activated protein kinases (p38 MAPK) in malignant mesothelioma cells." (PMID 31703415, 2019).
nephrolithiasis (1 paper, 2017). The presence of a calculus in the pelvis of the kidney; this is most often composed of mineral salts and proteins. "Note, thiazide diuretics are given to patients with nephrolithiasis to inhibit activity of the SLC12A2 cation chloride-coupled co-transporter while inhibitors of carbonic anhydrase may increase calcium excretion." (PMID 29296203, 2017).
Obesity (1 paper, 2024). Accumulation of substantial excess body fat. "It is incumbent on further studies to investigate if SLC12A2 gene expression affects BC risk through obesity/estrogen-related pathways." (PMID 38396187, 2024). "Our identification of phenotypes related to the top SNP of SLC12A2 indicates obesity may contribute to the increased BC risk linked to SLC12A2 gene expression." (PMID 38396187, 2024).
vestibular disorder (1 paper, 2020). Pathological processes of the vestibular labyrinth which contains part of the balancing apparatus. "Slc12a2-deficient M. musculus show loss of scala media, while homozygous Slc12a2 deficiency results in loss of endolymph volume, collapse of the otic vesicles with functional sensory hair cells, and a vestibular disorder phenotype in Danio rerio larvae." (PMID 32294086, 2020).
tumor (33 papers, 2009 to 2025). "Finally, we studied the expression of the screened SLC genes in CRC tumor tissues and normal tissues as well as investigated the role of SLC12A2 by loss of function and gain of function." (PMID 38396064, 2024). "From seven candidate NECSO regulators previously implicated in sodium homeostasis (NC1, CLT, DHPs, SLC12A2, SLC8A1, TRPM4, SLC9A1), intersection analysis identified two NECSO-associated DEGs - TRPM4 and SLC9A1 - showing consistent tumor-specific upregulation." (PMID 41235237, 2025). "Results showed that SLC12A2 was consistently and significantly upregulated in tumor tissues of both datasets." (PMID 38396064, 2024). "The majority of genes in the PAC-5 signature (LAMA3, E2F7, SLC12A2, and LRIG1) have been reported to be associated with tumour progression in various types of cancer." (PMID 31703415, 2019). "At the same time, we identified that SLC12A2 could promote tumor progression in CRC, which may serve as a potential therapeutic target." (PMID 38396064, 2024). "We thought the expression of SLC12A2 might be influenced by the tumor microenvironment, the different therapeutic drugs and so on, which needs to be studied by in vitro and in vivo experiments further." (PMID 38396064, 2024). "Hence, we evaluated the expression differences of SLC35B5 and SLC12A2 in tumor and normal tissues of CRC." (PMID 38396064, 2024). "Furthermore, we extracted expression data of SLC35B5 and SLC12A2 from paired tumor tissues and adjacent normal tissues in TCGA COAD and GSE41258." (PMID 38396064, 2024). "EVs secreted by invasive tumoroids (3D d10‐d14) included proteins promoting tumour growth (solute carrier family 12 member 2, SLC12A2; sodium bicarbonate cotransporter 3, SLC4A7), tumour invasion (fatty acid binding protein 5, FABP5) and immunosuppression (cluster of differentiation 73, CD73)." (PMID 38938900, 2023). "Interestingly, SLC12A2 expression was higher in tumour tissues than in normal pancreas tissues; however, it was rather highly expressed in the low-risk group, compared to the high-risk one." (PMID 31703415, 2019). "Tumor-specific stem-like cells (tSTM, cluster 0) exhibited strong upregulation of OLFM4, LEFTY1, SOD3, LCN2, SLC12A2, and MMP7, consistent with proliferative, inflammatory, and invasive phenotypes." (PMID 41282138, 2025). "In humans, the expression of SLC12A2, FERMT1, NCL, NOP56, and NOXA1 was significantly upregulated in human tumor cells compared to that in normal controls." (PMID 38886341, 2024). "The study identified tumor initiating cells which express ETS2, SLC12A2 and LEFTY1." (PMID 41282138, 2025). "Intriguingly, the EVs secreted by invasive tumoroids (3D d10‐d14) contained several unique proteins promoting tumour growth and invasion, for example, SLC4A7, SLC12A2, FABP5, PRDX1, CD59 and CD73, showing that specific oncogenic signals are loaded in EVs upon invasion." (PMID 38938900, 2023). "Treatment with 2 mM NaVPA–3 mM NaDCA significantly increased the expression of SLC12A2 in GBM5-1F and GBM5-2F cells (130% and 200%, respectively), but upregulation of SLC12A2 was not significantly different between GBM5-1F and GBM5-2F tumor cells after treatment with NaVPA–NaDCA." (PMID 41012498, 2025). "Further, in-depth analysis of TCGA-PRAD data revealed significantly higher gene expression profiles for SLC12A2 (P = 0.025), DDAH1 (P < 0.0001), NDRG1 (P = 0.0013), APOE (P < 0.0001), YWHAZ (P = 0.0385), and GDF15 (P < 0.0001), in PCa tumor tissue compared with non-tumoral adjacent tissue." (PMID 33483585, 2021).
cancer (21 papers, 2012 to 2025). A tumor composed of atypical neoplastic, often pleomorphic cells that invade other tissues. "We detected in PR elevated levels of enzymes (COX-2, ACSS2, FDPS, FASN, ACAT2, ACLY, SLC12A2) and metabolites (arachidonic acid and carnitine) involved in lipid metabolism, which have been linked to radioresistance of cancer cells." (PMID 38410100, 2024). "After discovering that DNA variation of KCC2 (SLC12A5) and NKCC1 (SLC12A2) affect the prognosis of cancer patients, we conducted a specific analysis of CCC mutation in cancer samples from TCGA database." (PMID 35372048, 2022). "Since the NKCC1 mutation has a prominently prognostic value on pan-cancer patients, we further analyzed the KCC2 (SLC12A5) and NKCC1 (SLC12A2) mutation, and we then queried 48,834 samples in 188 studies for a comprehensive analysis." (PMID 35372048, 2022). "We found 390 cases of mutations of KCC2 (SLC12A5) and NKCC1 (SLC12A2) in cancers." (PMID 35372048, 2022). "To investigate differential cation-chloride transportation patterns in tumors, we analyzed the differential expression of KCC2 (SLC12A5) and NKCC1 (SLC12A2) in pan-cancer tissues from TCGA database and normal samples from TCGA and GTEx Portal databases." (PMID 35372048, 2022). "Taken together, cation-chloride cotransporters KCC2 (SLC12A5) and NKCC1 (SLC12A2) have a certain impact on the survival of patients in pan-cancer, especially in KIRC, GBM, PRAD, THCA, BLCA, and CESC." (PMID 35372048, 2022). "Moreover, our univariate cox proportional hazards model showed that SLC12A2 was a protective factor in CRC while our basic experiments showed that SLC12A2 promoted cancer progression in CRC cells, this inconsistency needs to be explored further." (PMID 38396064, 2024). "In addition, we studied the relationship between the expression of KCC2 (SLC12A5) and NKCC1 (SLC12A2) in pan-cancer and immune checkpoint genes, including SIGLEC15, IDO1, CD274, HAVCR2, PDCD1, CTLA4, LAG3, and PDCD1LG2." (PMID 35372048, 2022). "Furthermore, we conducted a detailed Kaplan–Meier survival analysis of the specific effects of KCC2 (SLC12A5) and NKCC1 (SLC12A2) on patient survival in various cancers." (PMID 35372048, 2022). "Next, we analyzed all TIME elements and the enrichment scores of KCC2 (SLC12A5) and NKCC1 (SLC12A2) in pan-cancer, and found that the expression of KCC2 was significantly correlated with the increase in the number of immune cells, including B cells, Th2 cells, and M1 macrophages." (PMID 35372048, 2022). "Importantly, we analyzed the survival difference between the altered and unaltered group of KCC2 (SLC12A5) and NKCC1 (SLC12A2) among cancer patients from 66 databases." (PMID 35372048, 2022). "Next, we found that KCC2 (SLC12A5) and NKCC1 (SLC12A2) have a high frequency of CNV in pan-cancer, and significantly interfere with prognosis for cancer patients." (PMID 35372048, 2022). "Apart from cancer, miR-1246 has been shown to be involved in the regulation of chloride transport in epithelial cells by targeting CFTR and SLC12A2 and in the regulatory phenotype of T cells." (PMID 25880556, 2015). "Importantly, we analyzed the survival difference between the altered and unaltered group of KCC2 (SLC12A5) and NKCC1 (SLC12A2) among 10,967 pan-cancer patients, including disease-specific survival (DSS), PFS, and OS." (PMID 35372048, 2022). "What’s more, a recent study showed a specific SLC12A2 immunohistochemical staining pattern in precancerous and cancerous colonic UC lesions, which could be helpful for diagnosing dysplasia and cancer in UC and non-UC patients." (PMID 38396064, 2024). "In this study, we hypothesized that KCC2 (SLC12A5) and NKCC1 (SLC12A2), the major cation-chloride transporters, could predict the occurrence and development of cancers by regulating ion channels in pan-cancer, which may provide promising potential targets for clinical management strategies." (PMID 35372048, 2022).
SLC12A2 also shares sentences with these, for which no sentence is quoted: glioma (38 papers); neurological disorders (21); autism (20); Hydrocephalus (20); cerebral edema (16); Stroke (16); injury (13); brain disorder (12); neurodevelopmental disorder (12); Cognitive impairment (11); ischemic stroke (10); Ventriculomegaly (10); Down syndrome (9); Alzheimer disease (7); brain injuries (7); pulmonary edema (7); autism spectrum disorder (6); edema (6); Hyperglycemia (6); infection (6); Intraventricular hemorrhage (6); lung adenocarcinoma (6); Anxiety (5); Cerebral ischemia (5); esophageal squamous cell carcinoma (5); gastric cancer (5); Seizure (5); temporal lobe epilepsy (5); brain tumor (4); Hearing impairment (4).
A further 131 diseases each share a sentence with SLC12A2 in 4 papers or fewer.